PIK3R1 (phosphoinositide-3-kinase regulatory subunit 1)
Diseases named in the same sentence as PIK3R1 in open-access papers (continued):
Sharing a sentence is not in itself a finding about the gene and the disease.
cancer (continued). "Furthermore, other preclinical evidence shows that both MAPK1 and PIK3R1 could be potential pharmacological targets against human cancers." (PMID 36204096, 2022). "Notably, we further identified multiple reported malignancy‐related genes (e.g., MET, PIK3R1, PRKCA, PTEN, SHC1, and STAT3) upregulated in HCC272, and demonstrated that these genes were mainly enriched for cancer‐related functions, which were associated with broad drug resistance." (PMID 34105295, 2021). "Some of the most significant cancer genes identified by MutSig2CV based on recurrence, such as PIK3R1 (mutated in 4% of the tumors), were not selected by our expression-based approach, highlighting the independence of recurrence- and expression-based approaches." (PMID 32732999, 2020). "This indicates that PIK3R1 gene may have different functions in diverse cancers." (PMID 31402930, 2019). "Moreover, the correlation between increased RAB5A expression and decreased PIK3R1 expression in cancer warrants further investigation, as a possible feature of oncogenic adaptation where metastasis via Rab5-mediated cell migration progresses unchecked due to loss of regulation by p85α." (PMID 30650664, 2019). "In terms of CNAs, the cancer maintained the FGFR1 amplification and PIK3R1 deep deletion from the primary sample and acquired an amplification in AURKA in the metastatic sample." (PMID 40379787, 2025). "PIK3R1 is a regulatory subunit of the PI3Ks, which are part of the PI3K/AKT/mTOR pathway, a critical pathway in cancer that regulates cell survival and growth." (PMID 40869429, 2025). "In conclusion, PIK3R1 plays a crucial role in cancer as a regulatory subunit of PI3K, and the phenotypic variations observed in human cancers stem from a complex interplay of genetic factors, transcriptomic profiles, epigenetics, and proteomics." (PMID 40657399, 2025). "Alterations in genes such as PIK3R1 and AKT2 suggest hyperactivation of the PI3K/AKT pathway, which plays a critical role in promoting cancer cell survival, proliferation, and drug resistance." (PMID 39925800, 2025). "Super-enhancers have been found in genes involved in T-cell activation (IL2RA/CD25, CD30, and FYN) and known cancer genes (TP73, CCR4, TIAM2, NFATC1, NFATC2, and PIK3R1) in ATL cells." (PMID 38791169, 2024). "Topological analysis of the PPI network, using the STRING database and Cytoscape 3.10.2, identified seven core targets crucial in cancer pathways: CYP3A4, PIK3R1, PIK3CD, ESR1, AKR1C3, EGFR, and CYP19A1." (PMID 39204124, 2024). "The cancer hotspots lose their phosphomimetic nature with a charge reversal, negating the binding of PIK3CA and PIK3R1 through this domain." (PMID 38541623, 2024). "Schisandrin A (SchA), a good anti-cancer drug, significantly down-regulated EGFR, PIK3R1, and MMP9 but up-regulated cleaved-caspase 3, thus inhibiting the migration and promoting the apoptosis of MDA-MB-231 cells." (PMID 39190284, 2024). "The differential expression of PIK3R1, AKR1C3, EGFR, ESR1, PIK3CD, CYP3A4, and CYP19A1 across various cancer types and stages illuminates their potential as biomarkers for cancer progression and prognosis." (PMID 39204124, 2024). "The expression of PIK3R1 in different tumors and normal tissues by PAN cancer analysis on the TIMER website revealed that PIK3R1 was highly expressed in almost all the tumors." (PMID 36688087, 2023). "PIK3R1 and AKT1 both belong to the PI3K pathway, which is the most frequently altered pathway in cancer." (PMID 37895906, 2023). "PIK3R1 is the regulatory subunit of phosphoinositide 3 kinase (PI3K), which participates in the biological processes of various human malignant tumors." (PMID 37533633, 2023).
cancer (continued). "The degree of methylation of PIK3R5, PIK3R1, MAPK10, and CD40 genes in cancer tissues was significantly increased compared to normal tissue, while most of the remaining genes were reduced." (PMID 37666853, 2023). "It was found that POLE2, GABARAPL1, PIK3R1, NDC80, and TPX2 play critical roles in the response and overall survival in cancer patients under PD-L1 inhibitor treatment." (PMID 37240068, 2023). "The overlapping genes included five known cancer driver genes (including HGF, MET, and PIK3R1) and five putative FOXP2 targets, such as MET and PIK3R1, identified by chromatin immunoprecipitation assays in both mice and humans." (PMID 37668356, 2023). "The study of gene expression has also established ten hub proteins which significantly contribute to FI and cancer progression; among them VEGFA and PIK3R1 are the most significant for disease progressions." (PMID 36608061, 2023). "Our study conducted a comparatively comprehensive analysis of the role of PIK3R1 and PIK3R2 in a variety of cancers, contributing to further study of their potential mechanisms in cancer occurrence and progression." (PMID 35395865, 2022). "We further explored the PIK3R1 and PIK3R2 genetic alteration status in human cancers of TCGA cohorts using cBioPortal." (PMID 35395865, 2022). "In the present study, the transcriptional expression levels of PIK3R1 and PIK3R2 genes in pan-cancer were first visualized using the TIMER and GEPIA database." (PMID 35395865, 2022). "Among them, PIK3R1 and PIK3R2 plays opposite roles in 6 cancer types and similar roles in 3 cancer types." (PMID 35395865, 2022). "Somatic alterations including mutations and amplification in genes in the PI3K pathway, such as PTEN, PIK3CA, PIK3R1, and AKT, are often found in various kinds of human cancers including lung and activate the PI3K/AKT pathway, driving carcinogenesis." (PMID 33297998, 2020). "It was uncovered that PTEN, ARID1A, PIK3R1 and ZFHX3 were important suppressors that participated in cancer development." (PMID 32699528, 2020). "miR-29 represses p85 (PIK3R1) and miR-30 targets JUN, both of which are important in cancer progression." (PMID 32211051, 2020). "EGFR, IGF1R, LAMA2, MYLK, PIK3CA, PIK3R1, and MYLK are members of the focal adhesion pathway, whose dynamics are highly altered in cancer cells." (PMID 31024613, 2019). "The central gene is PIK3R1 in Module 0, which module contains eight DEGs related to classical cancer pathways (FCER1A, GNG11, IGF1, LIFR, PDK4, PIK3R1, RCAN2, and UGCG)." (PMID 31119098, 2019). "Thus, PIK3R1 might be a potential target for cancer therapy." (PMID 30497511, 2018). "Among these, the mRNA levels of PIK3R1 and CTNNB1 were increased more than 2-fold, and those of PIK3R3, PIK3CA and AKT3 were increased 1.6- to 1.9-fold after co-culture with cancer cells." (PMID 28173828, 2017). "The genes that were shared by three different cancers (i.e., FGFR3, EPAS1, SRC, and FOXD3) are shown in coral, and the genes that were shared by two types of cancers (i.e., PPARG, FOXO1, CDK4, NKX3-1, PIK3R1, PRKCB and EDNRB) are shown in light pink." (PMID 28178311, 2017). "KRAS, NRAS, HRAS, BRAF, PIK3CA, PIK3R1 and PTEN are key cancer-related genes in the RAS/RAF and PI3K/PTEN signaling pathways." (PMID 25120700, 2014). "Genes involved in signal transduction, an important type of pathways in cancer development, such as MARK14, VAV1 and PIK3R1 were also identified as gene signatures in this study." (PMID 21483478, 2011). "Mutations in PIK3R1 and RPL10 were not at high prevalence, yet exhibited some of the highest cancer effects in individual T-cell ALL patients." (PMID 38928295, 2024). "Both PIK3R1 and EGFR were involved in anti-cancer drug effects." (PMID 39190284, 2024).
cancer (continued). "Our analysis led to the identification of PIK3R1, CCND1, TERF2IP, SLC25A4, CAPN2, and TXN as hub genes, which could potentially serve as targets for interventions in both MN and cancer." (PMID 38846934, 2024). "Mechanistically, circRHBDD1 interacts with the m6A-binding protein YTHDF1 (YTH N6-methyladenosine RNA-binding protein F1), favoring PIK3R1 (phosphoinositide-3-kinase regulatory subunit 1) translation and activating the PI3K/AKT pathway that contributes to the metabolic shift in cancer cells." (PMID 38398157, 2024). "The subnetworks of ATF4, PIK3R1, and PIK3R3 filtered out from our study have been also shown to participate in TNF signaling pathway, since these hub genes involve immune regulation in cancer and AR disease." (PMID 37430199, 2023). "Notably, 18 of the 74 FECGs enriched in the PI3K-AKT pathway are known cancer driver genes, which include 4 core members of oncogenic MET signaling (HGF, MET, PIK3R1, and PIK3CA)." (PMID 37668356, 2023). "Notably, the expression of PIK3R1 and PIK3R2 were significantly correlated with the prognosis of 13 and 12 cancer types, respectively." (PMID 35395865, 2022). "Through literature review, we failed to retrieve any publication with a pan-cancer analysis of PIK3R1 and PIK3R2 from the perspective of overall tumors." (PMID 35395865, 2022). "As a result, PIK3R1 and FLT3 were recognized to be mutations that were not correlated to metastasis and the recurrence of a malignant tumor." (PMID 35664766, 2022). "The KEGG pathway results suggested that “ERBB signaling pathway”, “Proteoglycans in cancer”, “Ras signaling pathway” and “PI3K-Akt signaling pathway” may participate in the effect of PIK3R1 and PIK3R2 in tumorigenesis." (PMID 35395865, 2022). "Recently, several studies have identified that somatic driver mutations that are thought to contribute to EC pathogenesis, including PIK3CA, KRAS and PIK3R1, can exist in normal uteri without cancer." (PMID 36424602, 2022). "Our findings suggested that PIK3R1 and PIK3R2 could serve as prognostic markers for several cancers." (PMID 35395865, 2022). "For the positive–negative subjects (screening), 3 CNAs were detected in BC genes (ACVR2A, CUL3 and PIK3R1), and 5 SNPs were identified in 6 non-BC cancer genes (SNIP1, TBC1D10B, PANK1, PRKCA and RUNX2; SUPT3H)." (PMID 35589867, 2022). "Thus, a comprehensively understanding of the function of PIK3R1 and PIK3R2 in tumors will be necessary to develop better therapies and so we performed a pan-cancer analysis of them." (PMID 35395865, 2022). "AR, IGF1R, PDGFRB, PIK3R1, and SUFU involved in KEGG pathways in cancer." (PMID 34208639, 2021). "We first identified LIFR, PIK3R1, and MMP12 as novel prognostic biomarkers in this cancer." (PMID 31119098, 2019). "In cancer cells, nuclear p-STAT3-S705 can regulate the transcription of several autophagy-related genes such as BCL2 family members (e.g., BECN1, PIK3C3, CTSB, CTSL, PIK3R1, HIF1A, and BNIP3) and microRNAs with targets of autophagy modulators." (PMID 32565533, 2019). "To further test whether PIK3R1 were related to proliferation ability of HCC cells, we measured the effects of PIK3R1 expression levels on cancer cell proferation by MTT and Clonogenic assays." (PMID 30497511, 2018). "Meanwhile, increased PIK3R2 expression predicted better OS for CESC (HR = 0.50, P = 0.0038), TGCT (HR = 0, P = 0.0095) and better RFS for CESC (HR = 0.4, P = 0.02) and PCPG (HR = 0, P = 0.032), but we did not observe that PIK3R1 significantly influenced the prognosis of these three cancers." (PMID 35395865, 2022).
cancer (continued). "The set of genes proximate to these IS was significantly enriched in two datasets of cancer genes, including cancer drivers (genes such as BRAF, PIK3R1, RELN and TIAM2) suggesting that some koalas may harbour ERVs that could confer increased cancer susceptibility." (PMID 33637755, 2021). "Moreover, EGFR, PIK3R1, and PIK3CA are well-known cancer genes." (PMID 31024613, 2019). "Although PIK3R1 and PIK3R2 have been shown to serve opposite roles as tumor-suppressor gene and oncogenes in multiple tumors, evidence of their role in pan-cancer is lacking." (PMID 35395865, 2022). "These included the well‐studied cases of CTNNB1, PIK3R1, and SMAD4 proteins as well as proteins that are as yet not annotated as drivers, but are functionally connected to cancer pathways." (PMID 29572294, 2018). "Focusing on the expression characterization and immunological functions of PIK3R1 and YWHAZ, we found that PIK3R1 and YWHAZ play a non-negligible role in the maturation of T cells, a role that may also be present in a variety of cancers." (PMID 39403688, 2025). "Finally, we failed to obtain correlations between PIK3R1 or PIK3R2 expression and prognosis of other cancers." (PMID 35395865, 2022).
infection (12 papers, 2009 to 2025). The state of being infected such as from the introduction of a foreign agent such as serum, vaccine, antigenic substance or organism. "qRT-PCR and Western blot results indicated that PIK3R1 was up-regulated after S. enterica BNCC186354 infection, while L. reuteri ATCC 53,608 treatment inhibited its expression; meanwhile, the peaks that were annotated to PIK3R1 showed the same trend." (PMID 36980306, 2023). "PIK3R1, ITK and TMEM173 were identified as potential positional candidate genes associated with infection of Mycobacterium avium subspecies paratuberculosis in cattle." (PMID 32993537, 2020). "Next, normal mammary cells (MCF-10A and HMEC) were transduced with the PIK3CA- or PIK3R1-ReMB virus at a low multiplicity of infection (MOI = 0.3)." (PMID 29636477, 2018). "Meanwhile, we observed that certain biomarkers (SLC7A5, PDE4D, CXCR4, PER1, PIK3R1, HBA1, HBB) were elevated during the pre-infection phase (LTBI), while others (SOCS3, GZMK, HIS1H3B) were upregulated in the post-infection phase (ATB)." (PMID 40589756, 2025). "The expression levels of ITGA1, ITGA5, FAK, PIK3R1, PIK3CA and AKT1 were significantly higher in the 1 MOI L. salivarius-treated group, than in untreated cells at 2, 8, and 16 h post-PEDV infection." (PMID 34957282, 2021).
cardiovascular disease (5 papers, 2017 to 2025). "We proposed that longevity-associated genetic variants of PIK3R1 confer cell resilience, thereby mitigating the adverse intracellular effects associated with having a cardiovascular disease." (PMID 37561089, 2023). "PIK3R1 encodes Phosphoinositide-3-Kinase Regulatory Subunit 1 and was predicted to be a cardiovascular disease-related gene by a network topology analysis." (PMID 28710368, 2017). "Studies in human aging also show that sequence variations within PIK3R1 gene are significantly correlated with longevity, and individuals with different genotypes of PIK3R1 were associated with longevity through reduced mortality risk in cardiovascular disease." (PMID 36911092, 2023). "Furthermore, PIK3R1, which plays a role in kinase signaling, was highly expressed in cardiomyocytes, suggesting a connection between RA and cardiovascular disease." (PMID 40839671, 2025).
genetic disorders (4 papers, 2021 to 2025). "Identification of a series of human genetic disorders caused by constitutional PIK3R1 mutations over the past 10 years has given fresh impetus to the field and has been mechanistically illuminating." (PMID 38077044, 2024).
neurodegenerative disease (3 papers, 2017 to 2025). A disorder of the central nervous system characterized by gradual and progressive loss of neural tissue and neurologic function. "Further research will elucidate the precise molecular mechanisms by which PIK3R1 haploinsufficiency may impair neuronal and glial function and survival, providing critical new insights into neurodegenerative diseases." (PMID 40568112, 2025).
adenocarcinoma (1 paper, 2023). A common cancer characterized by the presence of malignant glandular cells. "Overexpression of PIK3R1 was shown to be significantly associated with a poor prognosis in adenocarcinoma." (PMID 36654811, 2023).
cardiac diseases (1 paper, 2021). "The screened hub genes, PIK3R1, SPNB2, and CRYAB, have been validated as credible molecular biomarkers using the mouse MI model and human blood samples, which may provide a novel therapy for cardiac diseases with increased proteotoxic stress." (PMID 34887920, 2021).
CNS tumors (1 paper, 2025). "Moreover, we identified pathogenic somatic variants in the following genes associated with CNS tumors: FGFR1 (in patient 15 with LGGNT and patient 16 with DNET) and PIK3R1 (in patient 15 with LGGNT)." (PMID 39859528, 2025).
PIK3R1 also shares sentences with these, for which no sentence is quoted: lipodystrophy (7 papers); dyslipidemia (5); Cerebral ischemia (4); Lymphadenopathy (4); clear cell renal cell carcinoma (3); heart failure (3); immunodeficiency 36 (3); angiosarcoma (2); bipolar disorder (2); bladder urothelial carcinoma (2); brain tumors (2); gallbladder cancer (2); gastrointestinal tumors (2); head and neck cancer (2); hyper-IgM syndrome (2); intrauterine growth restriction (2); kidney cancer (2); lymphopenia (2); malignant glioma (2); myocardial ischemia (2); Oral squamous cell carcinoma (2); retinoblastoma (2); spinal cord ischemia (2); urothelial carcinoma (2); viral disease (2); acquired lipodystrophy (1); acute monocytic leukemia (1); acute myocardial infarction (1); adenoma (1); aging (1).
A further 97 diseases each share a sentence with PIK3R1 in 1 paper.